MIR517C (microRNA 517c)
Synonyms: hsa-mir-517c; MIRN517C
Gene: MicroRNA gene on chromosome 19 (53,741,313 to 53,741,407, forward strand). Ensembl gene ENSG00000207838.
Gene Ontology:
Biological process: miRNA-mediated post-transcriptional gene silencing